TLR4 (toll like receptor 4)
Diseases named in the same sentence as TLR4 in open-access papers (continued):
Sharing a sentence is not in itself a finding about the gene and the disease.
infection (continued). "Next, we checked BPI expression in TLR4 knockout mice after infection with STM (WT) bacteria." (PMID 28861073, 2017). "The leptospiral LPS recognition by TLR4 is most probably the major factor influencing the susceptibility or resistance to infection and disease progression, since the lack of this receptor is enough to confer susceptibility to Leptospira sp." (PMID 28270811, 2017). "Given that TPL-2 is downstream of TLR4 and IL-1R-signaling and that TPL-2-deficent mice are more susceptible to bacterial infection due to reduced TNFα and IL-1β secretions, we analyzed the changes in microbiota following infection of WT and Map3k8–/–mice." (PMID 28759611, 2017). "Indeed, it has been described that B cells can produce IL-10 after recognition of S. Typhimurium LPS through TLR-4, which is relevant to the early stages of the infection." (PMID 28824622, 2017). "One main hypothesis formulates psychological stress induces inflammatory responses via Toll-like receptor 4 activation, similar to infection process." (PMID 28797292, 2017). "We found that APS can inhibit the expression of TLR4 in ECs following infection with CSFV at a later time, while co-stimulate and promote it at an early time point, indicating that APS can regulate innate immunity and vessel remodeling via TLR4 expression which has been proved in macrophages lately." (PMID 29018607, 2017). "Since TRIF mediates the signals from both TLR3 and TLR4 into the cell and pneumolysin has been suggested to activate TLR4, we first set out to investigate whether TLR4 is activated by T4R in our infection model." (PMID 26956584, 2016). "In this situation, upon LPS (a representative TLR4 agonist) challenge MSCs could promote an anti-inflammatory response from the bloodstream to the tissue site of infection." (PMID 27444640, 2016). "Also a significant change in the expression (MFI) of the phenotypic markers CD14 (up), CD163 (down) and TLR4+ (down) was measured after infection in both groups." (PMID 27606818, 2016). "It has been observed that TLR4-mutated strain C3H/HeJ is hyporesponsive to LPS and highly susceptible to infection by gram-negative bacteria such as Salmonella typhimurium and Neisseria meningitidis." (PMID 27293318, 2016). "Therefore, a tight regulation of TLR4 signaling is important in tissue homeostasis to avoid excessive inflammation and to induce tissue repair following infection or injury." (PMID 27293318, 2016). "TLR4 was ruled out as a major receptor in the detection of F. tularensis as TLR4-defective mice were no more susceptible to an inhalational infection with F. tularensis than wild-type mice and the survival rates were similar in both mouse strains." (PMID 27714591, 2016). "Expression of TLR4a, a Toll-like receptor 4 paralog, was also induced upon infection." (PMID 27101844, 2016). "Studies utilising TLR9−/− mice infected with L. major showed similar disease kinetics to those reported here with TLR2−/− and TLR4−/− mice, with increased lesion sizes and parasite burdens during the acute phase of infection with eventual control of the disease." (PMID 27716391, 2016). "Again, we suggest these previous findings support our hypothesis that PKR activation in response to TLR4 stimulation or infection is occurring through detection of host RNA species that are induced or modified through IRE1α RNAse activity." (PMID 27021640, 2016). "To determine whether differences in H. pylori infection in the gastric mucosa occurred following TLR4 or CD 25 blockage after infection, we measured the H. pylori colonization scores following pathological tests of the gastric mucosa." (PMID 26901645, 2016). "Infection of TLR4 mutant mice with BCG showed that TLR4 signaling may have a critical function in fine tuning of inflammation during chronic mycobacterial infection." (PMID 27458573, 2016).
infection (continued). "Given the size of LPS versus bacteria, the delayed thymic reaction following STm infection may be resulted from the longer time for bacteria enter the tissue and interact with TLR4 than single LPS molecular." (PMID 27142675, 2016). "A brown pigmentation indicated that TLR4 immunohistochemical staining within the neocortex of brains of mice infected by Acanthamoeba strain Ac55 was the highest at 2 dpi and markedly decreased during the time of infection." (PMID 27511368, 2016). "The relationship between TLR4 and infection has been widely investigated; after initial TLR mediated immune response triggered by LPS, it is possible for secondary response such as activation of endothelial cells that promotes the production of adhesion molecules to occur." (PMID 27652268, 2016). "Here we utilize mouse models to investigate the efficacy of a novel small molecule TLR4 antagonist, (+)-naloxone, the non-opioid isomer of the opioid receptor antagonist (−)-naloxone, in infection-associated preterm birth." (PMID 27819333, 2016). "Infection resulted in potent activation of PKR that was dependent on TLR4 and MyD88 signalling." (PMID 27021640, 2016). "Thus, lower estrogen during and following menopause would be expected to allow elevation of this pathway in the context of TLR4 triggers like infection." (PMID 26535108, 2015). "Likewise, LPS-binding protein (LBP) and myeloid differentiation primary response 88 (MYD88), also involved in TLR4 signaling, were significantly up-regulated after infection." (PMID 26018580, 2015). "The alteration in the level of expression of TLR2 and TLR4 may point the role of the innate immune system in the pathogenesis of this infection." (PMID 26622306, 2015). "Moreover, we did show a similar response from mammalian expressed endotoxin-free mS100A9 in vitro, and by adenovirus-mS100A9 infection in vivo, which resulted in the induction of IL-6 and IFNγ in a TLR4-dependent fashion." (PMID 25706559, 2015). "Notably, the infection was able to increase plasmatic cholesterol levels in MFD TLR4-/- mice at a later time (24 weeks)." (PMID 25668433, 2015). "Furthermore, an interaction between TLR4 and IL-17 has been demonstrated in other infections and comorbidities." (PMID 25706930, 2015). "This genetic variation in rs4986791 could alter the extracellular domain of the protein, which may modulate the interaction of ligands, such as lipopolysaccharide, with TLR4, leading to an impaired immune response and aggravated infection." (PMID 25928077, 2015). "In addition, the activation of FcεRI-dependent mast cell via TLR4 recognition plays an important role in the E. granulosus infection at 4-hour post infection, as indicated by the hyperexpressed molecules, such as FcεRI, MCP1, MCP3, and IRAK-4." (PMID 26252489, 2015). "This may be especially important after damage to the salivary gland since TLR4 is activated not only by infections but also by damaged self-tissue (DAMPs)." (PMID 26535108, 2015). "However, in the murine model of hepatic schistosomiasis used in this study, LPS levels in both portal and systemic circulation remained unchanged following infection, as did expression levels of the receptor, TLR4." (PMID 25116007, 2014). "We observed colocalization between TLR4 and Δisp2/isp3 during macrophage infection, suggesting that it is internalized together with the parasite, which could trigger IFNβ production." (PMID 24732131, 2014). "Collectively, these results indicate that expression of P. gingivalis lipid A structures that fail to engage TLR4 or function as TLR4 antagonists enables this pathogen to evade host innate immune detection and induce inflammation at sites distant from infection." (PMID 25010102, 2014). "Polymorphisms resulting in hypo-responsive TLR4 signaling are associated with susceptibility to Gram-negative sepsis as well as infections by E. coli and Meningococcus." (PMID 24497924, 2014).
infection (continued). "Interestingly, blocking of TLR4 before infection decreased epithelial IL-6 secretion, but increased the CREB-activated IL-10 production." (PMID 24489729, 2014). "However, we found that the LPS levels in portal and systemic circulation, as well as levels of TLR4 in HSCs remained unchanged following infection with schistosoma." (PMID 25116007, 2014). "Infection of Caco-2/TC7 cells with ETEC resulted in a stimulation of TLR4 inflammatory cascade." (PMID 24733511, 2014). "Increased PMN recruitment during infections of TLR4 deficient mice by Gram-negative pathogens Pseudomonas aeruginosa, Neisseria gonorrhea, Haemophilus influenzae has been reported previously." (PMID 24497924, 2014). "Besides that, entry of DV via Fc receptor, during a virus-enhancing antibody complex infection, preferentially switches off the TLR4 dependent signaling, due to a significant collapse of the TLR4 pathway." (PMID 25580138, 2014). "TLR4 expressed in cancer can prevent infection by microbial pathogens such as hepatitis B and C viruses, Helicobacter pylori, and human papilloma virus, which may cause cancer." (PMID 25179302, 2014). "Collectively, these results indicate that expression of P. gingivalis lipid A structures that fail to engage TLR4 or function as TLR4 antagonists enables this pathogen to evade host innate immune detection and contributes to inflammation at sites distant from infection." (PMID 25010102, 2014). "Such p38 MAPK-mediated suppression of TLR4 and TLR2 signaling may protect against an overwhelming immune reaction but may also lead to a higher risk of infection for the fetus and newborn." (PMID 25530682, 2014). "Triggering of macrophages by TLR2- or TLR4-activating bacteria impacts IL-10 secretion by these cells, suggesting a potential relevance of the described mechanism for modulating the course of the immune response during infection." (PMID 24227629, 2014). "The present study is the first to compare the in vitro and in vivo activation of TLR4 simultaneously in response to the infection with pathogenic and non-pathogenic strains of Acanthamoeba." (PMID 24633052, 2014). "However, a number of Gram-negative organisms have evolved mechanisms to modify their lipid A species, the component of bacterial LPS that directly activates the TLR4 complex, as a strategy to evade immune detection and establish infection." (PMID 25010102, 2014). "We conclude that these TLR4 SNPs affect constitutive receptor activity which impacts on the hosts ability to respond to LPS challenge leading to a dysregulated sub-optimal immune response to infection." (PMID 25365308, 2014). "To explore the impact that this activation might play in our infection model, we infected Tlr2−/−/Sigirr−/− and Tlr4−/−/Sigirr−/− mice." (PMID 25033044, 2014). "Intense PMN recruitment in HeJ mice may be a result of poor control of infection, or perhaps is initiated by an alternative response pathway that is normally suppressed by TLR4." (PMID 24497924, 2014). "To validate whether the activation of NF-κB in HSCs after infection was due to the LPS stimulation through TLR4 signaling, we detected the LPS levels in the portal and systemic circulation and TLR4 expression levels in HSCs after infection." (PMID 25116007, 2014). "Compared to wild-type mice, resistance to primary infection and to re-challenge was similar in TLR9-deficient or TLR6-deficient mice; it was greatly increased in TLR2-deficient mice but impaired in TLR3- or TLR4-deficient mice." (PMID 23853597, 2013). "In addition to cytokines, TLR4 stimulation also induces chemokines, which play an important role in recruiting cells to sites of infection or antigen presentation." (PMID 23457630, 2013). "To interrogate which PRR is essential for mycobacteria-induced MCP-2/CCL8 production in macrophages, we compared mRNA levels of mcp-2/ccl8 among macrophages from wild-type, TLR2−/−, TLR3−/− or TLR4−/− mice after infection with either BCG or H37Rv at an MOI 5 for 24 h." (PMID 23418602, 2013).
infection (continued). "In addition, we noted upregulation of Toll-like receptors (TLR-2 and TLR-4) as early as 2 weeks that persisted until 12 weeks post-infection." (PMID 23448601, 2013). "It is known that LPS-hyporesponsive mice (C3H/HeJ), which have a dysfunctional mutant TLR4, are highly susceptible to infection with Gram-negative bacteria." (PMID 23745121, 2013). "In fact, although we observed significantly lower baseline levels of the MHC II and costimulatory molecules, CD86 and CD40 on DCs in the absence of TLR4, the maturation and induction of these molecules was comparable to that of cells expressing TLR4 in response to hMPV infection." (PMID 24205331, 2013). "There has been great interest regarding the association of the TLR4 SNPs TLR4 896 A>G and TLR4 1196 C>T to susceptibility for infection and other non-infectious disease states." (PMID 24282567, 2013). "Indeed, in TLR4−/− infected lungs the level of cytokine expression induced by Mtb strain 02-171 was very much similar to that observed upon infection of WT mice with H37Rv." (PMID 23840651, 2013). "In contrast, P. brasiliensis recognition by TLR4 leads to an increased production of Th17 cytokines, enhanced pro-inflammatory immunity, and impaired expansion of regulatory T cells, resulting in a more severe form of infection." (PMID 23936560, 2013). "Infection of H.pylori induced the expression of TLR4 and activated NF-κB in AGS and GES-1 cells." (PMID 23437218, 2013). "Taken together, a combination of TLR4-dependent and independent mechanism may operate in tandem to regulate NF-κB activity in the colonic crypts of Tlr4−/− mice following CR infection." (PMID 24278135, 2013). "Interestingly, PAR-2 (mRNA), which is believed to be important in fungal (Alternaria) extract-mediated TSLP induction, is inhibited in a TLR4-dependent manner by A. fumigatus-infection in immunocompromised mice." (PMID 24063011, 2013). "Quantitative RT-PCR analysis revealed significantly (p < 0.05) increased CD14 and TLR4 expression in PBMC isolated from WMS calves but only TLR4 expression was significantly (p < 0.05) increased in PBMC from PA calves on day 4 post-BHV-1 infection." (PMID 22435642, 2012). "How would individuals with common mutations, such as the TLR4 Asp299Gly SNP, which are believed to have a negative impact on the receptor, have survived infections in the past?" (PMID 23730203, 2012). "SΦ874 infection caused chronic allodynia in TLR4+/+ HeJOuJ recipient mice, regardless of the donor bone marrow status." (PMID 22899994, 2012). "The increased TLR4 levels in the ears of Hyp-Duk/Y mice were probably caused by infection of Gram-negative bacteria that were unable to grow at the culture conditions." (PMID 23028440, 2012). "Numerous studies of two TLR4 polymorphisms, D299G (G896A) and T399I (C1196T), have revealed increased risk of infection with several Gram-negative organisms as well as septic shock." (PMID 22529866, 2012). "In the current study, we explore the expression of TLR4 under physiological condition as well as the corresponding mechanism involved in the defense infection and establishment of tolerance, as hypothesize by Gil Mor and co-worker." (PMID 22848642, 2012). "Due to the importance of TLR4 in the process of pathogen clearance we suggest that this represents a pathway in which probiotic immunomodulatory lactobacilli work to increase immunity and prevent infections." (PMID 22264349, 2012). "This demonstrates that TLR4 signalling is vital for the activation of T-cells during infection." (PMID 22724018, 2012). "Moreover, TLR4-competent mice have significantly higher serum levels of IFN-γ during early infection, and subsequent investigation demonstrated that NK cells in TLR4-competent mice produce significantly more IFN-γ after in vitro stimulation." (PMID 21912565, 2012). "By influencing immunological factors such as TLR4, important in the process of fighting pathogens, lactobacilli could facilitate pathogen recognition and infection clearance." (PMID 22264349, 2012).
infection (continued). "Since RSV activates TLR signaling (via TLR2 and TLR4) during infection, we next investigated whether TLR/MyD88 pathway is required for IL-1β secretion during RSV infection." (PMID 22295065, 2012). "The induction of the M2b phenotype, correlating with higher IL10 levels and a Th2-type response, was dependent on TLR4 and NE activities, suggesting that the engagement of TLR4 might be beneficial to the parasite at later stages of infection." (PMID 22523644, 2012). "This is further evidenced by our finding that a more severe disease is present in TLR4−/− mice along with the absence of an antibody response to SLP, suggesting that recognition of SLPs by TLR4 may play a role in determining the outcome of infection." (PMID 21738466, 2011). "The cecum from TLR4−/− and MyD88−/− had marked inflammatory cell infiltrates with oedema and epithelial disruption on days 3 and 7 post infection, that was significantly (p<0.05−0.01) greater than the mild inflammation in the cecum of infected wild-type, TLR2−/− or TRIF−/− mice." (PMID 21738466, 2011). "The early increase in the expression of TLR4 could be related with the decrease of the severity of the infection observed in the treated groups where the bacterial growth in the spleen and the liver decreased faster than in the infection control." (PMID 21813005, 2011). "This suggests that tlr-4 might be involved in P. falciparum recognition and host responses in humans, and that tlr-4 could contribute to the control of the infection." (PMID 21457584, 2011). "TLR4 is also important for infections by the retrovirus mouse mammary tumor virus (MMTV)." (PMID 21994762, 2011). "If both TLR2 and TLR4 respond similarly in the eye to infection with B. cereus, this may account for the unusually robust inflammation observed during this disease." (PMID 22163046, 2011). "Loss of TLR4 on immune cells will lead to immune suppression and increased susceptibility to infection but on the other hand protection of non-immune host tissue from inflammation is associated with TLR4 activation." (PMID 21513697, 2011). "Francisella LPS contains modifications that abrogate TLR4 recognition, the bacterium lacks genes that encode flagella and therefore does not activate TLR5, and TLR9 plays a minor role, if any, in providing the host with protection against infection in vivo." (PMID 21698237, 2011). "Interestingly, we also demonstrate activation of MAP kinase in response to infection with Δcpb amastigotes, again through a TLR-4 dependent mechanism." (PMID 21664694, 2011). "In addition, infection of mice with Ye leads to a massive reduction of CD4+ DCs in a TLR4- and TRIF-dependent manner." (PMID 21124820, 2010). "Various molecules are involved in TLR4 membrane regulation and could behave as new adjuvant therapies able to weaken the deleterious effects of exaggerated host response to infection." (PMID 20396414, 2010). "Nitrite levels are also lower in the sera of TLR4-deficient mice, compared to WT animals, at this time point of infection (data not shown)." (PMID 20442858, 2010). "By contrast, synthetic TLR4 agonists may boost the protective innate immune responses against infection." (PMID 20964825, 2010). "Finally, 5/25 C3H/HeJ mice died between 1 and 7 days post-infection (dpi), demonstrating the contribution of TLR4 signaling in preventing fatal bacterial infection." (PMID 20811584, 2010). "Small previous studies on the TLR4 Asp299Gly/Thr399Ile haplotype showed higher disease susceptibility and higher incidence of infections caused by Gram-negative microorganisms, but this was not supported by subsequent studies." (PMID 20525286, 2010). "The in vivo response to infection supports the conclusion that TcpC also suppresses Trif dependent effector functions, however, as Trif −/− mice have a functional Myd88 response, except for the cooperative TLR4 response to LPS." (PMID 20886104, 2010).